KEAP1 (kelch like ECH associated protein 1)
Diseases named in the same sentence as KEAP1 in open-access papers (continued):
Sharing a sentence is not in itself a finding about the gene and the disease.
lung carcinoma (continued). "Analysis indicated that CDKN2A, FAT1, MSH6, ARID1A, KEAP1, NF1, and SMAD4 mutation was more recurrent in patients with ERBB2 SNV/indels within the kinase domain compared with non-kinase domain in lung cancer." (PMID 35911441, 2022). "The activity of the KEAP1/NRF2 pathway is distinct in COVID-19 and lung cancer." (PMID 34277453, 2021). "SCD1 was previously shown to participate in aberrant lipid metabolism and promoted cell growth in lung cancer; therefore, its genetic and pharmacological inhibition could sensitize STK11/KEAP1 co-mutant cells to ferroptosis induction even in vivo." (PMID 34926310, 2021). "Studies with lung cancer, pancreatic cancer, and hepatocellular carcinoma cell lines showed that NRF2-KEAP1 status directly affects their proliferation rates since NRF2-negative cells proliferate slower, while KEAP1-deleted cells proliferate faster than their wild type counterparts." (PMID 32106613, 2020). "Compared with A549 or H460 lung cancer cell lines stably transfected with empty vector, mRNA levels of NRF2 and its target genes HO-1, GCLC, and FTH1 were significantly decreased after the cell lines were stably transfected with WT KEAP1." (PMID 32576270, 2020). "Subsequently, we validated this finding further in the H1299 lung cancer cells by showing the same set of five KEAP1 mutants failed to destabilize endogenous SOX9." (PMID 33173725, 2020). "In accordance with these findings, the depletion of endogenous KEAP1 by short hairpin RNA (shRNA)‐mediated knockdown or CRISPR‐mediated knockout in multiple liver and lung cancer cell lines led to a marked increase in the abundance of SOX9 protein, but not its mRNA levels." (PMID 33173725, 2020). "Despite the well-documented impact of KEAP1 and NFE2L2 mutations in NSCLCs and LCNEC, the prognostic role of KEAP1 methylation in lung cancer has not yet been clarified." (PMID 31159323, 2019). "In a more focused comparison with the most frequent neuroendocrine type of lung cancer, SCLC, type I LCNECs with STK11 and KEAP1 alterations exhibited a high degree of similarity with these carcinomas, as well as high expression of neuroendocrine genes and a profile of ASCL1high/DLL3high/NOTCHlow." (PMID 29535388, 2018). "Alterations in this pathway can co-occur with alterations in the RTK/Ras pathway, although KEAP1/NRF2 alterations are enriched in the ‘oncogene negative’ subset of lung cancers." (PMID 28145866, 2017). "Inferred TF activity of NFE2L2 was increased in mutant versus WT KEAP1 or NFE2L2 lung cancers; these differences are not observed at the gene expression level." (PMID 28139702, 2017). "Similarly, in lung cancer cell lines, MRTX1133 was unable to induce xenobiotic metabolism or cytokine gene expression, regardless of KEAP1 mutation status." (PMID 40890297, 2025). "Thus, these genes are mutated in 10–30% of lung cancer, whereas no mutations have been found in NFE2L2 or KEAP1 in pancreatic cancer." (PMID 37373496, 2023). "However, direct evidence in the setting of KEAP1-mutant lung cancer is lacking, which warrants further studies." (PMID 36632216, 2023). "Thus, the immunogenicity of KEAP1-mutant lung cancer cells is not likely to be the key determinant of the poor immunotherapy response." (PMID 36632216, 2023). "The absence of KEAP1 promoted metastasis in their lung cancer model expressing KRAS41." (PMID 36163484, 2022). "Moreover, modulation of Keap1 and PTEN can regulate cellular autophagy in lung carcinoma cells." (PMID 34576028, 2021). "Furthermore, the lung carcinoma datasets from The Cancer Genome Atlas (TCGA) showed that NRF2 or KEAP1 mRNA levels do not correlate with SOX9 mRNA levels." (PMID 33173725, 2020). "Together, these results suggest that genetic Keap1 status has less of an effect on metabolic TIF content in subcutaneous lung cancer allografts, and that not all cancer cell-intrinsic perturbations of metabolism cause detectable changes to the tumor nutrient milieu." (PMID 30990168, 2019).
lung carcinoma (continued). "Further prospective analyses in lung cancer tissues are ongoing to define whether some specific CpG sites of KEAP1, either a combination of them even if not consecutive, might have a better predictive or prognostic role in lung cancer patients." (PMID 31159323, 2019). "The results indicated that Keap1 mutations in Japanese individuals with NSCLC are not common, with observed frequencies demonstrated to be even lower compared with our previous in vitro analysis in lung cancer cell lines (50%)." (PMID 24137397, 2013). "In addition, the activity of NRF2 positively reflects erastin resistance in isogenic lung cancer cell models, regardless of Kelch-like ECH-associated protein 1(KEAP1) mutation, a molecule that represses NRF2 via its ubiquitin proteasomal degradation in normal conditions." (PMID 34926310, 2021).
lung adenocarcinoma (139 papers, 2014 to 2026). A carcinoma that arises from the lung and is characterized by the presence of malignant glandular epithelial cells. "Various types of cancer enhance NRF2 function in multiple ways, including genetic mutations in KEAP1 that disrupt their interaction and are found in 17% of lung adenocarcinoma (LUAD) cases." (PMID 40864301, 2025). "Anastasia’s research demonstrated that in Keap1-mutated lung adenocarcinomas, the dendritic cell-T-cell response is significantly inhibited, driving immunotherapy resistance." (PMID 40416989, 2025). "Mutations involving the KEAP1/Nrf2/Cul3 genes have been reported in 23% of lung adenocarcinomas (LUADs) and 34% of lung squamous carcinomas (LUSCs)." (PMID 40647497, 2025). "In 1817 KRAS-mutant lung adenocarcinomas, KEAP1 and SMARCA4 mutations correlated with metastasis and poor survival, while STK11’s impact varied by metastatic site and KEAP1 status." (PMID 40758706, 2025). "Kelch-like ECH-associated protein 1 (KEAP1) is mutated in 17% of lung adenocarcinomas and confers resistance to platinum therapy and immunotherapies." (PMID 41462606, 2025). "In this study, we have evaluated hot spot mutations of KEAP1 from the TCGA lung adenocarcinoma cohort, correlating differential expression of genes with the respective mutations." (PMID 38184997, 2024). "Concurrent loss-of-function mutations in STK11 and KEAP1 in lung adenocarcinoma result in significantly elevated expression of ferroptosis-protective genes, such as AKR1C1/2/3, and resistance to pharmacologically induced ferroptosis." (PMID 38698462, 2024). "Conversely, The lung adenocarcinoma patient with KEAP1 mutation and lower density of neutrophile granulocyte significantly shrink in 3 months (Figure 7C1,D1)." (PMID 38962454, 2024). "MSLN showed a 4.37 and 2.61 absolute fold upregulation in STK11 and KEAP1 mutated lung adenocarcinoma (LUAD) patient population, respectively." (PMID 39186767, 2024). "Mutations in STK11 and KEAP1 are associated with resistance to ICI treatment in lung adenocarcinoma, but these mutations are difficult to sufficiently predict the efficacy of ICI treatment in SMARCA4-UT." (PMID 39497014, 2024). "To characterize the KEAP1 driver mutations and study their effect on gene expression, we next investigated the RNA sequencing data from the available TCGA lung adenocarcinoma cohort." (PMID 38184997, 2024). "The KEAP1 gene is a tumor suppressor gene that is frequently mutated in lung adenocarcinoma patients, with a prevalence rate of 17%." (PMID 37633973, 2023). "STK11 and KEAP1 were considered to be associated with poor prognosis in patients diagnosed with lung adenocarcinoma." (PMID 37384291, 2023). "In lung adenocarcinoma, mutations in Kelch-like ECH-associated protein 1 (KEAP1), which constitutively activates NRF2, are required for glutathione synthesis." (PMID 36982568, 2023). "According to the previous studies, approximately 20–30% of lung adenocarcinoma harbor the KEAP1 mutations which correlate with poor prognosis." (PMID 37301854, 2023). "For example, KEAP1 mutations in lung adenocarcinoma are associated with xenobiotic metabolism in both TCGA samples and CCLE cell lines, in agreement with the known role of the NRF2/KEAP1 pathway in the regulation of xenobiotic response." (PMID 35565274, 2022). "In this study, the multiplatform data from TCGA were adopted to identify subsets of lung adenocarcinoma with KEAP1/NFE2L2 mutations." (PMID 35371318, 2022). "In contrast, we only observed relatively low-level copy number gains and losses of KEAP1, even though a high mutation rate of KEAP1 was detected in lung adenocarcinoma (LUAD) and squamous cell carcinoma." (PMID 35453346, 2022). "We used macrophage-like LPS-stimulated RAW264.7 cells, since such macrophages have vital roles in regulating inflammatory and antioxidant responses and A549—a lung adenocarcinoma cell line—owing to its point mutation in the Keap1 allele." (PMID 35362892, 2022).
lung adenocarcinoma (continued). "In our study, multiplatform data from The Cancer Genome Atlas (TCGA) were acquired to identify two subtypes of lung adenocarcinoma harboring KEAP1/NFE2L2 mutations." (PMID 35371318, 2022). "As well, the Aox1 genewas reported as an NRF2 binding site in the Keap1-mutated Lung adenocarcinoma patients." (PMID 35180880, 2022). "Two subtypes of KEAP1/NFE2L2-mutant lung adenocarcinoma were identified based on both patient and cell line samples, and genomic and clinicopathological features of KEAP1/NFE2L2 mutations were characterized." (PMID 35371318, 2022). "It is imperative to mine the underlying mechanisms and characteristics of KEAP1/NFE2L2/CUL3 mutations in lung adenocarcinoma and accelerate the investigations of the pathway and the targeted drugs." (PMID 34617407, 2021). "Concurrent mutations in STK11/KEAP1 act as a major driver in primary resistance to PD1 blockade in KRAS-mutated lung adenocarcinoma." (PMID 34204917, 2021). "Literature evidence reported that in lung adenocarcinoma epithelial cells, mutations in Keap1 genomic locus result in the increase of NRF2 pathway activation." (PMID 35071051, 2021). "More research needs to be done to figure out the underlying molecular mechanism of mutations of the KEAP1/NFE2L2/CUL3 pathway in lung adenocarcinoma, and there is still a long way to go to target these mutations as a new therapeutic strategy." (PMID 34617407, 2021). "KRAS mutant lung adenocarcinoma patients with concurrent inactivating mutations in the tumor suppressor genes of KEAP1 and STK11 have demonstrated lower clinical response rates treated with standard chemotherapy or immunotherapies." (PMID 32560187, 2020). "In this study, we systematically carried out an integrated multi-omics analysis to explore the correlation between KEAP1 mutations and DNA methylation and its effect on gene expression in lung adenocarcinoma (LUAD)." (PMID 32327612, 2020). "KEAP1 mutation is associated reduced leukocyte infiltration of tumor microenvironment in lung adenocarcinoma." (PMID 32206449, 2020). "Mechanistically, the mutations in KEAP1 found in lung adenocarcinoma patients lead to the activation of the NRF2 pathway and an increase in HMOX-1." (PMID 33228209, 2020). "As 20% of lung adenocarcinomas (LUAD) harbor KEAP1 mutations and thus elevated NRF2 activity, we tested the correlation between KEAP1 mutations and immune parameters in this tumor entity." (PMID 32978520, 2020). "KEAP1 mutations, which typically decrease ubiquitylation and turnover of Nrf2, are found in 16.8% (154/915) of recent lung adenocarcinoma samples (MSK-IMPACT), while CUL3 mutations are infrequent at 1.5% (14/915)." (PMID 31581742, 2019). "Using a CRISPR/Cas-9-based approach in a mouse model of KRAS-driven lung adenocarcinoma, it was examined the effect of KEAP1 loss in lung adenocarcinoma development and hyperactivates NFE2L2 expression." (PMID 30060526, 2018). "Somatic KEAP1 mutations were most frequently found in lung adenocarcinoma (LUAD), followed by LUSC and liver hepatocellular carcinoma (LIHC)." (PMID 30150714, 2018). "Immunohistochemical analysis of Nrf2 and Keap1 in tumor specimens was performed in a total of 104 lung adenocarcinoma patients with the status of EGFR gene mutations or EGFR wide-type." (PMID 29587953, 2018). "As above repeatedly mentioned, about 20% of KRAS mutant lung adenocarcinomas display KEAP1 loss, often associated with KRAS mutations." (PMID 30060526, 2018). "A large-scale study, The Cancer Genome Atlas (TCGA), identified ∼17% KEAP1 mutations in lung adenocarcinoma (LUAD) patients." (PMID 29050246, 2017). "CUL3, encoding the ubiquitin ligase adaptor that binds to Keap1 and degrades Nrf2, was also associated with radiation resistance in adenocarcinoma of the lung." (PMID 27109210, 2016).
lung adenocarcinoma (continued). "Consistent with TCGA network data, the strongest association between KEAP1 mutation and radiation resistance was in adenocarcinoma of the lung (IC=0.352; P=0.0224, calculated using the empirical permutation test)." (PMID 27109210, 2016). "Consistent with this function, we find that pharmacologic inhibition of SLC33A1 with IXA4 selectively reduces viability of KEAP1-deficient lung adenocarcinoma cells that have elevated levels of glutathione, mimicking the sensitivity of these cells to genetic deletion of SLC33A1." (PMID 41757008, 2026). "Moreover, comprehensive research evaluating 450 cases of lung adenocarcinoma with KEAP1 mutations revealed that KEAP1-mutated tumours were associated with lower tumour-infiltrating lymphocytes and cytotoxic T lymphocyte infiltration in tumour tissue." (PMID 40650126, 2025). "KEAP1 mutation in lung adenocarcinoma reduces the dendritic cell and T cell responses that drive immune therapy resistance, leading to immune resistance in lung adenocarcinoma patients." (PMID 38884095, 2024). "It is still unclear whether KEAP1 mutation is detrimental to immunotherapy of lung adenocarcinoma (LUAD) patients, we try to analyse the exact changes in the TME in LUAD patients with KEAP1 mutations and to identify key factors influencing prognosis." (PMID 38962454, 2024). "In this study, we show that in the GSEA analysis of TCGA lung adenocarcinoma RNA-seq data, the KEAP1 mutations in R320 and R470 were associated with enhanced Tumor Necrosis Factor alpha (TNFα) – Nuclear Factor kappa subunit B (NFκB) signaling as well as MYC and MTORC1 pathways." (PMID 38184997, 2024). "Similarly, two subtypes were identified in 20 lung adenocarcinoma cell lines harboring KEAP1/NFE2L2-mutations (C1 and C2 groups)." (PMID 35371318, 2022). "Moreover, in a Kras-driven lung adenocarcinoma, Keap1 loss leads to the appearance of high-grade invasive adenocarcinomas that are typically associated with increased metastases." (PMID 35534896, 2022). "Mutations in KEAP1 were first discovered in human lung adenocarcinoma cell lines, wherein a glycine-to-cysteine substitution within the Nrf2-binding domain of Keap1 reduces its affinity for Nrf2, resulting in loss of canonical Nrf2 regulation and constitutive Nrf2 hyperactivation." (PMID 36552553, 2022). "Furthermore, copy number analysis also detected the loss of chromosome 9 in these tumors, which the Keap1 and Setd2 genes, both of which have been shown to function as tumor suppressors in KrasG12D-driven mouse model of lung adenocarcinoma." (PMID 35482806, 2022). "Indeed, 20% of the KRAS-mutant lung adenocarcinoma carry loss-of-function mutations in kelch-like ECH associated protein 1 (KEAP1) gene." (PMID 33499022, 2021). "Therefore, our further research needs more samples to provide a more accurate subgroup analysis of KEAP1/NFE2L2/CUL3 pathway mutations so as to exhibit a deeper insight into KEAP1/NFE2L2/CUL3 pathway mutation in lung adenocarcinoma progression." (PMID 34617407, 2021). "In addition, KEAP1-mutated lung adenocarcinoma showed distinctive DNA methylation pattern which make it distinguishable from their wild-type counterparts." (PMID 32327612, 2020). "Overall, DNA methylation in KEAP1-mutated lung adenocarcinoma compared to normal tissues followed a distinct pattern along the gene coding sequence, with lower methylation levels mostly near the transcription start site and higher methylation levels mostly at gene body." (PMID 32327612, 2020). "Additionally, lung adenocarcinoma with simultaneous mutations in Keap1 and Kras showed an increased glutamine utilization for energy production." (PMID 31078780, 2019). "KEAP1 deletion or mutation is frequently found in KRAS-driven lung adenocarcinomas and may present an obstacle to ERK inhibitor therapy in these tumors." (PMID 31439014, 2019).